GDF15 (growth differentiation factor 15)
Diseases named in the same sentence as GDF15 in open-access papers (continued):
Sharing a sentence is not in itself a finding about the gene and the disease.
sarcopenia (continued). "The relationship between GDF-15 and pathologies that associate with sarcopenia will be discussed in this review." (PMID 36361969, 2022). "This review analyzes GDF-15 in human conditions specifically focusing on its association with muscle manifestations of sarcopenia, mitochondrial myopathy, and autoimmune and viral myositis." (PMID 36361969, 2022). "Next, we analyzed serum GDF15 levels to assess its diagnostic significance for the prediction of sarcopenia in patients with COPD." (PMID 35845807, 2022). "The allocated diagnostic performance of GDF-15 as a serum marker for sarcopenia in COPD is of 70% sensitivity and 90% specificity, with an area under the curve (AUC) of 0.83." (PMID 36361969, 2022). "The results of univariate analysis showed that old age (odds ratio [OR]: 1.084, 95% CI: 1.028–1.144, p = 0.003) and elevated serum GDF15 levels (OR: 5.396, 95% CI: 2.313–12.588, p < 0.001) were associated with sarcopenia in patients with COPD." (PMID 35845807, 2022). "Contrary to the health-promoting effects of exercise, GDF15 is also elevated in diseases associated with muscle weakness such as sarcopenia and mitochondrial myopathy." (PMID 34831213, 2021). "Elevated GDF15 in cognitive frailty may indicate chronic elevation, similar to sarcopenia or mitochondrial myopathy, and may be associated with reduced muscle mass and decreased brain white matter." (PMID 41273998, 2026). "Notably, in older adults with sarcopenia and in critically ill older adults, inverse associations between GDF15 and quadriceps muscle mass or exercise capacity have been reported." (PMID 41273998, 2026). "In contrast, the diagnostic accuracy of GDF-15 for sarcopenia was poor." (PMID 41286529, 2025). "Importantly, eGFRdiff remained significantly associated with GDF‐15, a marker increasingly linked to sarcopenia, even after adjusting for eGFRcr or eGFRcys." (PMID 40700030, 2025). "Furthermore, colocalization analysis identified a significant shared SNP site between eQTL expression of the GDF15 gene and the risk of sarcopenia, with a high Bayesian posterior probability verification of 99.9%, indicating a common genetic basis." (PMID 40119457, 2025). "Preoperative assessment of IL‐6 and GDF‐15 levels, alongside evaluation of sarcopenia, could enhance risk stratification and inform personalised treatment strategies." (PMID 41380167, 2025). "Growth Differentiation Factor 15 (GDF15) is a mitokine expressed in response to various stresses whose circulating levels increase with age and are associated with numerous pathological conditions, including muscle wasting and sarcopenia." (PMID 38808117, 2024). "As such, the associations between GDF‐15 and sarcopenia observed in the current study, may be the result of senescence and mitochondrial dysfunction." (PMID 38890783, 2024). "Due to the association of GDF‐15 with both sarcopenia and frailty, it may serve as a pragmatic stratification tool for evaluating older patients at risk." (PMID 38890783, 2024). "Recently, a possible association of GDF15 with sarcopenia and muscle mass loss has been reported." (PMID 38808117, 2024). "This study also showed an association between GDF15 and sarcopenia but whether there was racial diversity in sarcopenia risk in relation to GDF15 levels was not reported." (PMID 39668628, 2024). "Age and BMI are associated with pathological processes, including sarcopenia, which may increase GDF15." (PMID 37523061, 2023). "Therefore, univariate analysis and multivariate analysis were used to explore the association between age, GDF15, and sarcopenia in patients with COPD." (PMID 35845807, 2022). "However, the involvement of GDF‐15 in various pathophysiological processes leading to sarcopenia may partly contribute to this association." (PMID 40700030, 2025). "Thus, sarcopenia may be an underlying prognostic factor for the development of postoperative complications and short-term risk, where GDF-15 may be involved." (PMID 34063283, 2021).
sarcopenia (continued). "Adults with sarcopenia showed elevated GDF-15 (k = 5, SMD: 0.26, 95% confidence interval (95%CI): 0.03-0.50, I2 = 64%, P = 0.03) and reduced IGF-1 (k = 11, SMD: -0.40, 95%CI: -0.54 - -0.27, I2 = 36%, P < 0.01) compared to controls without sarcopenia." (PMID 42202210, 2026). "Because GDF15 reflects mitochondrial distress in the myocardium and in skeletal muscle, it represents a molecular hinge between sarcopenia and HFpEF." (PMID 41596265, 2026). "In contrast, in sarcopenia and mitochondrial myopathy, circulating GDF15 levels remain chronically elevated and correlate with reduced muscle mass and strength." (PMID 41273998, 2026). "The results identified the regulation of the downstream target of metformin, GDF15, for sarcopenia traits and adverse events." (PMID 40119457, 2025). "By elucidating the combined influence of IL‐6, GDF‐15 and sarcopenia on perioperative outcomes and long‐term survival, this study aims to enhance prognostication, optimise preoperative preparation and refine postoperative care strategies for patients with BC." (PMID 41380167, 2025). "GDF-15 plasma levels appear to be elevated in mobility-limited older adults with frailty and sarcopenia." (PMID 41286529, 2025). "Patients with both sarcopenia and high IL‐6 or GDF‐15 levels exhibited significantly worse overall survival and cancer‐specific survival in multivariate Cox regression analysis." (PMID 41380167, 2025). "Intriguingly, greater early reduction in GDF-15 levels was correlated with reversal of sarcopenia, suggesting a dual role of GDF-15 in both cancer progression and cachexia modulation." (PMID 41294666, 2025). "Elevated IL‐6 and GDF‐15 levels were significantly correlated with the presence of sarcopenia (p = 0.04 and p = 0.03, respectively)." (PMID 41380167, 2025). "In univariate logistic regression, high GDF‐15 was found to be a predictor of sarcopenia (OR 2.07, 95%CI 1.08–3.95, p = 0.03)." (PMID 41380167, 2025). "This retrospective study investigates the roles of the biomarkers interleukin‐6 (IL‐6) and growth differentiation factor‐15 (GDF‐15), in the context of sarcopenia, assessing their impact on oncological and survival outcomes." (PMID 41380167, 2025). "While mounting evidence suggests a link between GDF-15 and sarcopenia, the precise function of GDF-15 in the reduction of muscle mass and function remains uncertain." (PMID 40400914, 2025). "Nonetheless, we cannot conclude that patients in this risk group should not undergo surgery, as plenty of patients were identified with CSS > 1 year, who also showed both traits (high GDF‐15/sarcopenia)." (PMID 41380167, 2025). "Further exploration of the mechanisms by which metformin affects GDF15 and sarcopenia is needed to confirm these findings and develop targeted therapies." (PMID 40119457, 2025). "Patients with both sarcopenia and high GDF‐15 had higher tumour stages (p < 0.01), more often positive surgical margins (p < 0.01) and inferior OS (p < 0.01) and CSS (p = 0.02)." (PMID 41380167, 2025). "To the best of our knowledge, we presented the first study showing the prognostic significance of IL‐6 and GDF‐15 in relation to sarcopenia and adverse outcomes in patients undergoing RC for BC." (PMID 41380167, 2025). "ApoE4 status and plasma p-tau217 (AD), NfL (neurodegeneration), GFAP and IL-6 (inflammation), GDF-15 (senescence/sarcopenia) will be evaluated in all subjects (n = 1,662) both at the baseline and at the end of the study (12 months)." (PMID 40400914, 2025). "Several studies have suggested that GDF-15 is associated with poor muscle function, and serum GDF-15 levels can be used to assess sarcopenia in COPD patients." (PMID 41517298, 2025). "Growth differentiation factor 15 (GDF-15) has been proposed as a potential biomarker for the geriatric syndromes of frailty and sarcopenia." (PMID 41286529, 2025).
sarcopenia (continued). "GDF‐15 was significantly higher in patients with sarcopenia (P < 0.01) and patients with frailty (P < 0.001) compared with non‐sarcopenic and non‐frail patients, respectively." (PMID 38890783, 2024). "Nevertheless, with PMA and the biomarker GDF-15 validated for muscle weakness, we have a strong surrogate of sarcopenia." (PMID 39310722, 2024). "Systemic GDF‐15 was significantly higher in patients with either sarcopenia (P < 0.01) or frailty (P < 0.001) compared with patients without the conditions." (PMID 38890783, 2024). "The optimum cutoff of GDF‐15, estimated by Youden's Index, was 2166 and 1541 pg/mL for frailty and sarcopenia, respectively." (PMID 38890783, 2024). "It is known that GDF15 signaling is involved in some pathological processes, such as apoptosis, cellular senescence, fibrosis, and atrophy/sarcopenia." (PMID 39643709, 2024). "Our results are in keeping with other studies which showed significant relationship of GDF-15 with sarcopenia, frailty, gait speed and poor physical function in older adults." (PMID 38510450, 2024). "The present study defined the optimum cut‐off for GDF‐15, related to the presence of sarcopenia and frailty, respectively." (PMID 38890783, 2024). "In the sub‐group of patients assessed for potential sarcopenia, we found a significantly higher proportion of patients with GDF‐15 > 1541 pg/mL in the moderate and severe CCI weighted index (P > 0.001)." (PMID 38890783, 2024). "The median concentration of GDF‐15 was 2669.2 pg/mL in the total cohort and 2365.5 pg/mL in the subgroup of patients assessed for potential sarcopenia." (PMID 38890783, 2024). "This is in line with recent results from a study on stable COPD patients, which found that serum GDF‐15 levels were significantly higher in patients with sarcopenia compared with non‐sarcopenic patients." (PMID 38890783, 2024). "Optimum cut‐off points of GDF‐15 relating to sarcopenia and frailty were 1541 and 2166 pg/mL, respectively." (PMID 38890783, 2024). "Our data show that serum GDF15 levels can effectively distinguish patients with COPD with sarcopenia, and we also determined the cutoff value." (PMID 35845807, 2022). "The nomogram models based on serum GDF15 level, age, and BMI further improved the predictive ability of identifying patients with sarcopenia." (PMID 35845807, 2022). "Several studies have demonstrated significantly increased circulating levels of GDF15 in patients with sarcopenia and malignancy, including CRC." (PMID 35566740, 2022). "The aim of this study was to assess the clinical value of circulating GDF15 in prospectively screening for sarcopenia in patients with COPD and to determine the cutoff value for use in clinical practice." (PMID 35845807, 2022). "We found for the first time that serum GDF15 levels represent a simple and efficient indicator of sarcopenia in COPD patients." (PMID 35845807, 2022). "In conclusion, serum GDF15 levels can be used to accurately and easily evaluate sarcopenia in patients with COPD." (PMID 35845807, 2022). "The sensitivity and specificity for predicting sarcopenia based on the serum levels of GDF15 were 65.12 and 87.84%, respectively (the cutoff point was 357.5 pg/mL, and the AUC value was 0.827)." (PMID 35845807, 2022). "The pattern of traumatic acid was similar to that of GDF‐15, a recognized marker for sarcopenia (P for trend <0.001)." (PMID 34939349, 2022). "Our results from the development set and validation set indicated that higher serum GDF15 levels (> 357.5 pg/mL) showed a good predictive ability for sarcopenia." (PMID 35845807, 2022). "Further studies are needed to confirm or refute if measuring circulating GDF-15 levels is helpful to recognize sarcopenia early in elderly individuals." (PMID 36361969, 2022). "This study was the first to clarify the predictive value of serum GDF15 levels for sarcopenia in patients with COPD." (PMID 35845807, 2022).
sarcopenia (continued). "Correlation analyses were further performed to investigate the relationship between traumatic acid, GDF‐15, and the parameters of sarcopenia and nutrition status." (PMID 34939349, 2022). "Further studies are needed to clarify the relationship between circulating GDF-15 levels and muscle wasting in patients with CD and sarcopenia-related outcomes." (PMID 35449185, 2022). "First, we found that GDF15 in patients with sarcopenia was significantly higher than that in controls (438.3 ± 180.9 pg/mL vs. 269.1 ± 104.3 pg/mL, p < 0.001)." (PMID 35845807, 2022). "This is especially apparent for GDF15 production in muscle, which can be induced both by exercise and by muscle disease states such as sarcopenia and mitochondrial myopathy." (PMID 34831213, 2021). "Since GDF-15 appears to play a role in numerous other pathological conditions, such as cancer and sarcopenia, further investigation of the GDF-15 influence in different cell types and disease conditions is warranted." (PMID 33105809, 2020). "In humans, circulating GDF15 levels are significantly higher in subjects with sarcopenia or muscle atrophy with respect to healthy subjects of comparable age." (PMID 32477368, 2020). "Furthermore, sarcopenia patients also had higher GDF15 than non-sarcopenia patients (1360 vs. 1076, P = 0.003)." (PMID 41016991, 2026). "In previous studies, we and others have identified biomarkers such as growth differentiation factor 15 (GDF15) and lipoprotein‐associated phospholipase A2 (Lp‐PLA2) as predictors of sarcopenia in patients with COPD, with reported AUCs of approximately 0.827 and 0.744, respectively." (PMID 41582634, 2026). "Collectively, these findings position GDF15 as a whole-body stress integrator that mechanistically bridges adipose inflammation, muscular bioenergetic failure, and cardiac dysfunction within the obesity–sarcopenia–HFpEF triad." (PMID 41596265, 2026). "Therefore, elevated GDF11 constitutes an independent predictor of sarcopenia, operating through direct catabolic signaling distinct from GDF15’s metabolic effects." (PMID 40969368, 2025). "Clinically, serum GDF15 >1,200 pg/mL predicts 3.4-fold higher sarcopenia risk independent of comorbidities." (PMID 40969368, 2025). "Additionally, our analysis points to GDF15 as a potential target for future investigations, though more research is required to confirm its role in modulating sarcopenia." (PMID 40119457, 2025). "The interplay between IL‐6, GDF‐15 and sarcopenia suggests a complex network of inflammatory and metabolic processes that may act synergistically to worsen outcomes in patients with BC." (PMID 41380167, 2025). "The results suggested a potential negative association between high GDF15 expression and sarcopenia traits, as well as adverse events such as osteoporosis and death." (PMID 40119457, 2025). "Therefore, we were able to identify high‐risk patient groups prior to cystectomy by determining serum IL‐6, serum GDF‐15 and sarcopenia." (PMID 41380167, 2025). "Current evidence highlights GDF15 as a key factor in sarcopenia, suggesting that metformin's effect on sarcopenia may be mediated through its effect on GDF15." (PMID 40119457, 2025). "Moreover, GDF-15 has been proposed as a biomarker for sarcopenia, a clinical condition characterized by muscle atrophy and weakness." (PMID 40400914, 2025). "After categorising patients into groups by the presence of IL‐6 or GDF‐15 and sarcopenia, significant differences in OS and CSS could be shown between these groups (log‐rank in all cases p < 0.01)." (PMID 41380167, 2025). "Patients with sarcopenia had higher levels of GDF‐15 in serum (p = 0.03)." (PMID 41380167, 2025). "Odds ratios for having sarcopenia or frailty according to the dichotomous level of GDF‐15." (PMID 38890783, 2024).
sarcopenia (continued). "Our results remained significant after adjusting for the effect of age, sex, co‐morbidity, and levels of CRP, indicating that GDF‐15 may be a potential biomarker of sarcopenia in multimorbid acutely admitted older patients." (PMID 38890783, 2024). "Moreover, c-GDF15 level is inversely correlated with muscle strength in both healthy subjects and patients, supporting its use as a biomarker of sarcopenia and muscle dysfunction." (PMID 38808117, 2024). "Notably, given the multicomponent concept of frailty and sarcopenia, it is highly likely that the predictive value of GDF‐15 increases when it is combined with several other markers in a predictive model." (PMID 38890783, 2024). "As such, it is unclear whether GDF‐15 can be utilized as a biomarker of sarcopenia and frailty in the early stages of hospitalization due to the potential effects of acute illness." (PMID 38890783, 2024). "Moreover, the present study defined the optimum cutoff for GDF‐15 related to the presence of sarcopenia and frailty, respectively." (PMID 38890783, 2024). "In particular, studies showed that c-GDF15 level could easily predict sarcopenia in patients with chronic obstructive pulmonary disease and in aged mice and humans." (PMID 38808117, 2024). "In addition, our study showed a significant association of MCR with sarcopenia, as well as fat mass indices in pre-frail older adults, with a significant increase in TNF-α and GDF-15." (PMID 37371414, 2023). "Hence, GDF-15 is a detrimental mediator for muscle–brain crosstalk and a potential target for the treatment of sarcopenia and cognitive dysfunction." (PMID 37577356, 2023). "However, the application of GDF15 levels and cutoff points to predict sarcopenia in patients with COPD warrants caution in clinical practice." (PMID 35845807, 2022). "The AUC value for predicting sarcopenia with GDF15 was 0.801 (p < 0.001)." (PMID 35845807, 2022). "Serum GDF15 levels could be used to accurately and easily evaluate sarcopenia in patients with COPD." (PMID 35845807, 2022). "Furthermore, the serum levels of GDF15 in patients with sarcopenia were significantly higher than those in controls." (PMID 35845807, 2022). "This pattern was similar to that of GDF‐15, a recognized sarcopenia‐related factor." (PMID 34939349, 2022). "Some studies link sarcopenia, frailty, and reduced physical performance in older individuals with higher levels of circulating GDF-15, other studies report gender-specificity or fail to observe an association, or report that GDF-15 levels cannot predict sarcopenia." (PMID 36361969, 2022). "In this study, we demonstrated that the association of serum GDF15 levels with sarcopenia in patients with COPD was independent of age." (PMID 35845807, 2022). "Collectively, these findings suggest that serum GDF15 levels may serve as clinically feasible biomarkers for the prediction of sarcopenia in patients with COPD." (PMID 35845807, 2022). "GDF-15 must be investigated further to understand its pathophysiological effects on sarcopenia." (PMID 34943268, 2021). "In our study, patients with high serum levels of GDF-15 showed severe appetite loss, systemic inflammation and poor PS, but not sarcopenia or body weight loss." (PMID 34638326, 2021). "In contrast, with mitochondrial myopathy or sarcopenia, GDF15 levels remain chronically elevated, presumably resulting in vastly different biological outcomes, similar to most metabolic hormones, where chronic hypo- or hyper-physiological levels are implicated in disease states." (PMID 34831213, 2021). "Additionally, some mitokines potentially function as biomarkers for the diagnosis of sarcopenia, such as growth differentiation factor 15 (GDF15) and fibroblast growth factor 21 (FGF21)." (PMID 34881083, 2021). "As far as muscle atrophy and sarcopenia, there is debate on whether GDF15 is to be considered protective or detrimental." (PMID 32477368, 2020).